PPP6R1 (protein phosphatase 6 regulatory subunit 1)
Description:
Regulatory subunit of protein phosphatase 6 (PP6). May function as a scaffolding PP6 subunit. Involved in the PP6-mediated dephosphorylation of NFKBIE opposing its degradation in response to TNF.
Synonyms: KIAA1115; PP6R1; SAPS1; SAP190
Tractability: PROTAC: ubiquitination databases record sites on it; its protein half-life has been measured.
Target class: Protein phosphatase regulatory subunit; Phosphatase; Enzyme; Protein Phosphatase
Gene: Protein-coding gene on chromosome 19 (55,229,776 to 55,259,070, reverse strand). Ensembl gene ENSG00000105063.
Subcellular location: Cytoplasm
Subcellular location (Human Protein Atlas): Cytosol
Pathways (Reactome):
Vesicle-mediated transport: COPII-mediated vesicle transport
Gene Ontology:
Molecular function: protein binding; protein phosphatase regulator activity; small GTPase binding; protein phosphatase binding
Biological process: regulation of signal transduction
Cellular component: cytosol; lamellipodium; nucleus; cytoplasm
Genetic constraint (gnomAD): Loss-of-function variants: 39 observed, 95.63 expected, observed/expected ratio (o/e) 0.41, 90% interval 0.31 to 0.53. The synonymous counts are far from expectation, so gnomAD's model fits this gene poorly and the ratio says little. Missense variants: 1,181 observed, 1,098.4 expected, observed/expected ratio (o/e) 1.08, 90% interval 1.02 to 1.13. Synonymous variants: 549 observed, 458.17 expected, observed/expected ratio (o/e) 1.2, 90% interval 1.12 to 1.29.
Homologues: Orthologues: chimpanzee PPP6R1 (99% identical), macaque PPP6R1 (92% identical), dog PPP6R1 (89% identical), pig PPP6R1 (88% identical), rat Ppp6r1 (84% identical), mouse Ppp6r1 (84% identical), rabbit PPP6R1 (82% identical), guinea pig PPP6R1 (82% identical), tropical clawed frog ppp6r1 (56% identical), Drosophila melanogaster fmt (23% identical), Caenorhabditis elegans saps-1 (17% identical). Paralogues in human: PPP6R3 (46% identical), PPP6R2 (44% identical).
Diseases named in the same sentence as PPP6R1 in open-access papers:
PPP6R1 is named in the same sentence as 4 diseases in open-access papers, as found by Europe PMC text mining. Sharing a sentence is not in itself a finding about the gene and the disease. The quoted sentences say what the papers report.
cardiac diseases (1 paper, 2024). "In the case of PPP6R1, Protein Phosphatase 6 Regulatory Subunit 1, no previous information related to CNVs has been found in the context of cardiac diseases or any other context." (PMID 38473795, 2024).
tumor (1 paper, 2016). "Interestingly, some of them function as tumor suppressors (e.g. BCL2L11, MXD1, WWOX, BNIP3L, and DMTF1) or are candidate tumor suppressors having anti-proliferative properties and DNA repair abilities (e.g. LRRC2, RPA4, PPP6R1, SPEN, RAP1GAP and CISH) (see discussion section)." (PMID 26918450, 2016).
PPP6R1 also shares sentences with these, for which no sentence is quoted: infection (2 papers); glioblastoma (1).